CXCR4 (C-X-C motif chemokine receptor 4)
Diseases named in the same sentence as CXCR4 in open-access papers (continued):
Sharing a sentence is not in itself a finding about the gene and the disease.
prostate carcinoma (continued). "The data show that presence of complex between CXCR4, TTC7B and PI4KIIIα in PC3-CXCR4 and VCaP cells demonstrating this interaction is predominant among prostate cancer cells." (PMID 37996444, 2023). "To identify the novel interacting proteins contributing to the CXCR4-mediated bone tumor growth, we developed a stable model of PC3 prostate cancer cells with knockdown and overexpressing CXCR4." (PMID 38239314, 2023). "To further characterize how the CXCR4-PI4KIIIα axis promotes PCa metastasis, here we identify CXCR4 binds to PI4KIIIα adaptor proteins TTC7 and this interaction induce plasma membrane PI4P production in prostate cancer cells." (PMID 36865146, 2023). "To determine the endogenous interaction of CXCR4 with PI4KIIIα adaptor protein TTC7B, we immunoprecipitated prostate cancer cells with CXCR4 and immunoblotted with TTC7B, PI4KIIIα and CXCR4." (PMID 37996444, 2023). "PEDF also downregulates CXCR4 and TNF, as well as increasing TNF-related apoptosis-inducing ligand to activate immunosurveillance in prostate cancer." (PMID 36555293, 2022). "In the treatment of prostate cancer, myricetin promotes prostate cancer cell apoptosis and antimetastatic effects by inhibiting PIM1 and by disrupting its interaction with CXCR4." (PMID 36091790, 2022). "Well in line, overexpression of CXCL12 receptors (CXCR4 and CXCR7) by breast and prostate cancer cells induces chemotaxis along CXCL12 gradients to allow for colonization of the bone." (PMID 34831167, 2021). "Alike, treatment with AMD3100 (plerixafor), a CXCR4 antagonist, blocked SDF1/CXCR4 interaction leading to a regression of CSC subpopulation in breast, colon and prostate cancer." (PMID 34354950, 2021). "Most importantly, treatment of mice with HSC-mobilizing agents, such as the CXCR4 antagonist AMD3100 or G-CSF, also resulted in the egression of prostate cancer cells from the bone marrow into the peripheral blood." (PMID 34831167, 2021). "In addition, the findings in this study also illustrated the possibility for CXCR4 to be a potential therapeutic target for treating prostate cancer, and inhibiting exosomal CXCR4 secretion may be a novel therapeutic against tumor development in the initial stage of prostate cancer." (PMID 34659412, 2021). "In prostate cancer cells, this CAF phenotype can induce ROS production and C-X-C motif chemokine receptor 4 (CXCR4) and IL-6 receptor expression and thereby cell migration and invasion." (PMID 34834295, 2021). "In prostate cancer, CAF-mediated CXCL12/CXCR4 axis induces the differentiation of monocytes and possibly M1 cells into pro-tumor M2 cells." (PMID 34447750, 2021). "In prostate cancer, the CXCL12/CXCR4 axis is crucial for the initial establishment of bone metastases in the endosteal niche, which is severely compromised by the blockade of the CXCL12/CXCR4 axis." (PMID 35006432, 2021). "Emodin inhibited NF-κB, lowered CXCR4 activation at the transcription level, thus prohibiting the invasion and migration of DU145 prostate cancer cells." (PMID 34073059, 2021). "Very recently, we found that in peripheral blood from prostate cancer (PCa) patients, NK cells show enhanced CD9, CD49a and CXCR4 expression." (PMID 34638439, 2021). "The microRNA, MIR-128-1, and two genes—CXCR4 and THSD7B—in the LCT locus all have putative roles in prostate cancer." (PMID 33193640, 2020). "In several prostate cancer cell lines, acetyl-l-carnitine acted as an anti-prostate cancer agent by inhibiting the production of chemokines CXCL12 and CCL2 as well as CXCR4 (chemokine ligand-receptor) and pro-inflammatory cytokines (IFN-γ and TNF-α)." (PMID 32370025, 2020).
prostate carcinoma (continued). "For example, suppression or down-regulation of DPP4 promotes prostate cancer progression via reduced degradation of its substrate CXCL12, leading to enhanced signalling via CXCR4 and increased invasion and metastatic spread to peripheral organs in vivo." (PMID 33143089, 2020). "In breast and prostate cancers, stromal cell-derived factor 1 (SDF-1) and its receptor CXCR4 are responsible for attracting tumor cells to the bone marrow." (PMID 33262947, 2020). "Although not investigated in this study, we have previously observed concomitant expression of HIF1-α and the chemotactic receptor, CXCR4, in DU145 prostate cancer cells under H2O2 oxidative stress." (PMID 32719369, 2020). "Both CXCR5 and CXCR4 are involved in metastasis of PCSLC prostate cancer stem-like cells, and inhibition of CXCR4 alters the homing of quiescent stem-like prostate cancer cells to bone." (PMID 30873179, 2019). "A limited number of pre-clinical studies have demonstrated that the inhibition of the CXCR4/CXCL12 pathway using CXCR4 antagonists, including Plerixafor and CTCE-9908, reduced bone metastatic burden in breast and prostate cancer models." (PMID 31500357, 2019). "The role of CXCL12 in homing to the bone is further supported by in vitro migration assays that demonstrated that the breast and prostate cancer cells migrate towards CXCL12 and osteoblasts, which is dependent on CXCR4." (PMID 29642534, 2018). "The over-expression of CXCR4 and CXCR7 by breast and prostate cancer cells increases their vascular ability and bone colonization in mouse models." (PMID 29461491, 2018). "In that study, two scFvs were selected against CXCR4 and their inhibitory effects on CXCL12- mediated prostate cancer cell activation was investigated." (PMID 28491282, 2017). "The other chemokine receptor gene whose expression correlated with that of CXCR4 was CX3CR1, which is expressed in NK cells, subsets of monocytes, CD4+ and CD8+ T cells, as well as prostate cancer and various experimental cancers and cancer cell lines." (PMID 29088715, 2017). "TGF-β treatment alone increased mRNA levels of PTHrP, CXCR4 and CTGF in breast and prostate cancer cells." (PMID 29156807, 2017). "Meanwhile, we also observed a significant increase in HSC factors/markers (KITLG, CXCR4 and FGF1) in Tie-2High PC-3 cells when compared to the Tie-2Low population, further suggesting that Tie-2High prostate cancer cells are similar to HSCs." (PMID 25978029, 2016). "Overall, these results show that homeostatic levels of CXCR4 protein require CXCR7 expression, and that CXCR4 expression is required for CXCL12-mediated motility in LNCaP prostate-cancer cells." (PMID 25884570, 2015). "Proposed markers distinguishing prostate cancer from benign tissues include: CD117, CD133, CXCR4, and CD34." (PMID 25595903, 2015). "Together, these data showed that acute stimulation by chemokines CXCL11 and CXCL12 changed the intracellular immunoreactivity of CXCR4 and CXCR7 in AD-LNCaP prostate-cancer cells." (PMID 25884570, 2015). "In addition, a high CXCR4 expression was found to correlate with bone metastasis in prostate cancer, while a neutralizing antibody against CXCR4 may block the bone metastasis of prostate cancer." (PMID 25846512, 2015). "In this study, we assessed the levels of prominent prostate cancer markers: CD117, CD133, CXCR4, and CD34, on circulating cells from prostate cancer patients before and after radical prostatectomy." (PMID 25595903, 2015). "A similar up-regulation of CXCR4 in response to CXCL12, mediated through NF-κB, has been reported in prostate cancer cells." (PMID 25774696, 2015). "In prostate cancer cells, CXCL12 and CXCR4 play a key role in invasion and metastasis, leading to development and expansion of osseous metastasis." (PMID 24472670, 2014).
prostate carcinoma (continued). "We propose these results indicate the importance of CXCL8-driven CXCR4 and CCR2 expression in the prostate cancer cells, which increases their capacity to respond to each of these stromal-derived chemokines." (PMID 24970800, 2014). "In addtion, prostate cancer progenitor cells express CXCR4 and often these cells are resistant to current chemo and radiation therapy practices, thus, combination therapy with anti-CXCR4 strategies consisting of CTCE-9908 may prevent the further spread of tumor in patients." (PMID 24472670, 2014). "A close relationship between the regulation of the CXCR4/SDF1 axis and PGK1 has been shown for prostate cancer, influencing the “angiogenic switch” through the regulation of angiostatin." (PMID 24376734, 2013). "At the same time, chemokine receptor CXCR4 and its ligand CXCL12 mediate the adherence of prostate cancer cells to ECs, facilitating tumor invasiveness and metastatic progression." (PMID 24386459, 2013). "By blocking such SDF1α -CXCR4 axis, through AMD3100, we have shown that this axis covers a pivotal role in prostate cancer cell migration and that it is probably crucial in MSC conditioned medium attractive effect." (PMID 23301946, 2013). "This determines a close relationship between the regulation of the CXCR4/SDF1 axis and PGK1 in prostate cancer." (PMID 24376734, 2013). "Prostate cancer frequently metastasizes to the bone, and previous studies implicate key role for CXCL12/CXCR4 signaling in bone metastasis." (PMID 23902739, 2013). "CXCR4 expression in prostate cancer enhances the invasive, metastatic ability of tumor cells in the presence of CXCL12 ligand, while inhibition of CXCR4 decreases metastatic ability." (PMID 24259307, 2013). "The effect of SDF-1 and a CXCR4-specific antagonist, AMD3100, on human prostate cancer PC-3 cell proliferation and protein kinase B (Akt) signaling was assessed." (PMID 24137439, 2013). "To verify that CXCR4 expression is upregulated in prostate tumor initiating cells, we examined CXCR4 levels in CD44+/CD133+ prostate cancer progenitor cells and total cell populations in the DU145 and PC3 cell lines by flow cytometry." (PMID 22359577, 2012). "The studies reported herein show that the CXCR4/CXCL12 axis, a key regulator of tumor dissemination, plays a role in the maintenance of prostate cancer stem-like cells." (PMID 22359577, 2012). "Activation of the CXCR4/CXCL12 signaling pathway significantly increases the CD44+/CD133+ population for both PC3 and DU145 prostate cancer cell lines in a dose dependent manner (up to 3.5-fold and 2.6-fold increase, respectively)." (PMID 22359577, 2012). "It is known that activation of the CXCR4/CXCL12 pathway alters the adherence, migration, and invasion of cancer cells, including prostate cancer." (PMID 22359577, 2012). "CXCL12 is an important input in CXCR4+ prostate tumor initiating cells and leads to an elevated activation of the PI3K pathway and more robust proliferation of prostate cancer progenitors." (PMID 22359577, 2012). "We used gain- and loss-of-function approaches to study (i) how SLUG regulates the CXCR4/CXCL12 axis, and (ii) the functional role of CXCL12 in SLUG-induced migration and invasion of human prostate cancer cell lines." (PMID 22074556, 2011). "The ligand for CXCR4 is CXCL12 (also known as stromal derived factor 1; SDF1) and is highly expressed at sites of prostate cancer metastasis including lymph nodes, bone, lungs and liver." (PMID 21603150, 2011). "Because our data show that SLUG positively regulated both CXCL12 and CXCR4; therefore, we assessed the role of CXCL12 in SLUG-mediated prostate cancer invasion." (PMID 22074556, 2011). "To further study the possible role of CXCR4 in the regulation of CCL20 expression, we evaluated the mRNA expression of CCL20 in prostate cancer cells with low and high CXCR4 expression using real-time RT-PCR." (PMID 19340288, 2009).
prostate carcinoma (continued). "CXCL12 and its receptor CXCR4 along with MMP-2 and MMP-9 are related with prostate cancer perineural invasion." (PMID 18983683, 2008). "The distribution and expression of CXCL12, CXCR4, MMP-2 and MMP-9 in human prostate cancer and in tumor cells invading nerve tissue were studied with immunohistochemical staining." (PMID 18983683, 2008). "In the progression of prostate cancer PNI, CXCL12 and CXCR4 secreted by tumor cells and nerve tissue induce tumor cells to migrate toward nerves." (PMID 18983683, 2008). "Our research aims to study CXCL12, CXCR4, MMP-2 and MMP-9 expression in prostate cancer PNI using in vitro experiments, animal model experiments and human prostate cancer tissue." (PMID 18983683, 2008). "The expression of CXCL12, CXCR4, MMP-2, and MMP-9 in human prostate cancer were higher than those in hyperplastic prostate tissues (P < 0.05)." (PMID 18983683, 2008). "We reported previously that CXCR4 expression is correlated with tumor grade, and that CXCL12 signaling through CXCR4 triggers the adhesion of prostate cancer cells to bone marrow endothelial cells." (PMID 16859559, 2006). "Studies have confirmed that CXCL12 chemokines and their receptors CXCR4 and CXCR7 may be involved in the initiation and EMT process of prostate cancer metastasis." (PMID 41347146, 2025). "In prostate cancer, androgen hormone induces the activity of transcriptional regulator, ERG, which increases the expression of CXCR4 thereby enhancing the pro-tumoural effects of CXCL12-CXCR4 signalling pathway." (PMID 40852716, 2025). "In addition to close collaboration with CXCR7, using biophysical and biochemical methods, CXCR4 is found to form induced heterodimers with the cannabinoid receptor 2 (CB2) in human breast and prostate cancer cells." (PMID 41347146, 2025). "CXCL12 treatment stimulates the migration and invasion of prostate cancer cells, which are inhibited by the CXCR4 antagonist AMD3100 and the combination of CXCR4 or CXCR7, suggesting that CXCL12-CXCR4/CXCR7 signaling axes can be potential targets for PCa intervention." (PMID 41347146, 2025). "IL8 from TEC was reported to play a mediating role in prostate cancer progression; meanwhile, CXCR7, CXCR4, and VEGF are angiocrine factors TEC stimulate angiogenesis and enhance survival of TEC in an autocrine manner, thus supporting tumor progression and metastasis." (PMID 38515582, 2024). "In PC-3 tumor xenograft models, AMD3100 has been shown to inhibit tumor growth and reduce microvessel formation by inhibiting CXCR4/Akt signal transduction, and CTCE-9908 has been shown to reduce tumor spread and angiogenesis in an orthotopic prostate cancer model." (PMID 38727318, 2024). "As long as a combination of PD-L1- and CXCR4-targeted therapies have been tested for TNBC patients, a relevant treatment combination could be tested in prostate cancer patients to examine their therapeutic impact." (PMID 38727318, 2024). "Inhibition of CXCR4 also showed promise, with pre-clinical testing of Plerixafor reducing the establishment of bone metastases in bone-metastatic prostate cancer mouse models, yet it failed to impact the growth of pre-established bone metastases." (PMID 37025604, 2023). "Although it has not been reported in prostate cancer, there is evidence that CXCR4 is affected by epigenetic modification in metastatic prostate cancer." (PMID 37190171, 2023). "For example, miR-494-3p has been shown to inhibit CXCR4 expression after transcription processes in prostate cancer; lncRNA UCA1 activates CXCR4 through inhibiting the activity of miR-204 to promote the progression of prostate cancer." (PMID 37190171, 2023). "However, in osteosarcoma and bone-metastatic breast and prostate cancer cells bisphosphonates downregulated CXCR4, which suppressed CXCL12-CXCR4 signaling-induced invasion though this phenomenon needs to be tested in vivo." (PMID 37025604, 2023).
prostate carcinoma (continued). "The CXCL12/CXCR4 axis is one of the most important axes for the interaction between bone microenvironment and tumor cells and was shown to be important for AKT activation in breast as well as prostate cancer." (PMID 34064589, 2021). "According to a recent study, ROSI is capable of downregulating C-X-C motif chemokine 12 (CXCL12)-induced migration, invasion and PI3K/Akt activation in a prostate cancer cell line, through the inhibition of the CXCL12/C-X-C chemokine receptor type 4 (CXCR4) axis." (PMID 34631571, 2021). "As such, enhanced expression and exaggerated activation of GPCRs and G proteins (e.g., CXCR4 and Gγ9) may represent crucial mechanisms responsible for the enhanced activation of the oncogenic ERK1/2 pathway in prostate cancer." (PMID 33493514, 2021). "Fortunately, AMD300, a CXCR4 inhibitor approved by the United States Food and Drug Administration (FDA), has already been shown to disrupt tumor-stromal interactions, sensitizing cancer cells to docetaxel-based chemotherapy in prostate cancer." (PMID 34568309, 2021). "On the other hand, in advanced pancreatic ductal adenocarcinomas (PDAC), intact TGF-β/SMAD4 pathway facilitates cancer progression; in advanced prostate cancer, bone-borne TGF-β induces osteoclastogenesis and bone metastasis by activating chemokine (C-X-C motif) receptor 4 (CXCR4)." (PMID 34917620, 2021). "Exosomes enriched with HSP70 were secreted from prostate cancer cells, inducing the engagement of TLR2 and phosphorylation of NF-κB, resulting in upregulating expression of CXCR4 in MDSCs and eventually leading to the accumulation of MDSCs into tumor microenvironment (TME)." (PMID 34659412, 2021). "Plerixafor (AMD3100), a CXCR4 antagonist approved by the FDA, was shown in a subcutaneous xenograft mouse model of human prostate carcinoma to dissociate the prostate cancer cells from their sanctuary site (the BM) and thus sensitize them to chemotherapy treatment." (PMID 33987095, 2021). "Since CXCL12 is a classical ligand of CXCR4 and CSF-1/CSF-1R crosstalk from prostate cancer cells to recruited macrophages was previously identified, we proposed that the feedback crosstalk from macrophages to cancer cells is partly mediated by CXCL12/CXCR4." (PMID 34069563, 2021). "In this study, we demonstrated the recruitment of MDSCs can be promoted by exosomes derived from prostate cancer cells, which could upregulate chemokine (CXC motif) receptor 4 (CXCR4) via the TLR2/NF-κB signalling pathway." (PMID 34659412, 2021). "Interestingly, CXCR4, the bona fide CXCL12 receptor and CXCR7, a scavenger receptor overexpressed in prostate cancers, have been both identified as direct target genes of HIC1." (PMID 33227080, 2020). "In a study to assess the role of the CXCL12/CXCR4 axis in prostate cancer migration and tumor invasiveness, it was reported that CXCL12 activation of prostate cancer cell lines, PC3 and LNCaP, increased their migratory potential via the upregulated expression of several metalloproteinases (MMPs)." (PMID 32585812, 2020). "The immune score, as well as the expression of CXCR4 and GPR183 in prostate cancer tissues, could be potential indexes for the prognosis of prostate cancer." (PMID 33194726, 2020). "Despite the low levels of endogenous CXCR4 expression in LNCaP and DU-145 cells, it was found that CXCL12 facilitated increased adhesion of these prostate cancer cells to monolayers of endothelial cells and immobilized matrix through enhanced expression of α5 and β3 integrins." (PMID 32585812, 2020). "We observed increased phosphorylated AKT (p-AKT) and CXCR4 expression, independent of any ligands, which were abrogated by a ROS scavenger in prostate cancer cells." (PMID 32719369, 2020).